RN7SKP214 (RN7SK pseudogene 214)
Gene: Miscellaneous RNA gene on chromosome 22 (37,055,033 to 37,055,347, reverse strand). Ensembl gene ENSG00000201078.
Homologues: Orthologues: chimpanzee 7SK (98% identical). Paralogues in human: 7SK (75% identical), RN7SKP180 (74% identical), RN7SKP3 (74% identical), RN7SKP176 (74% identical), RN7SKP203 (73% identical), RN7SKP245 (73% identical), RN7SKP255 (72% identical), RN7SKP50 (72% identical), RN7SKP25 (72% identical), RN7SKP71 (72% identical), RN7SKP79 (72% identical), RN7SKP9 (72% identical), and 284 more.